RBM20 (RNA binding motif protein 20)
Diseases named in the same sentence as RBM20 in open-access papers (continued):
Sharing a sentence is not in itself a finding about the gene and the disease.
cardiomyopathy (continued). "TTNtv are associated with incomplete penetrance and late onset heart failure, whereas patients with i.e., pathogenic RBM20 or LMNA mutations are affected by comparably early cardiomyopathies with incomplete penetrance." (PMID 33260757, 2020). "Mutations of RBM20 gene are known to cause cardiomyopathies because RBM20 regulates circular RNA production from the Titin (TTN) gene." (PMID 31092860, 2019). "DCM hearts expressed longer TTN isoforms, which is known to cause disease in RBM20-mediated cardiomyopathy." (PMID 28903782, 2017). "RBM20 is expressed preferentially in cardiac tissue and implicated in cardiomyopathies, while RBM20 antagonists represent a potential therapeutic target in HF management." (PMID 28510119, 2017). "The authors confirmed segregation within the larger pedigree of the variant in RBM20, a recently identified cardiomyopathy gene, providing statistical support for RBM20 causing DCM." (PMID 24705294, 2014). "Previous description on the up-regulation of these genes is consistent with the phenotype of the Rbm20-/- rats that causes heart failure and signs of cardiomyopathy." (PMID 24367651, 2013). "RBM20 is a cardiac splicing regulator whose dysfunction causes severe cardiomyopathies." (PMID 42177204, 2026). "Loss of RBM20 causes an abnormal intracellular calcium handling, which may relate to the arrhythmogenic presentation of RBM20 cardiomyopathy." (PMID 35804579, 2022). "In 2009, the first case of RBM20-associated human cardiomyopathy was described." (PMID 34575212, 2021). "In this regard, loss of RBM20 causes an abnormal intracellular calcium handling, which may relate to the arrhythmogenic presentation of RBM20 cardiomyopathy." (PMID 32789749, 2020). "These impaired mechanisms of thin-filament activation and tension production may contribute to cardiac dysfunction and the associated cardiomyopathies in humans, rats, and mice bearing RBM20 mutations that influence titin splicing." (PMID 27524973, 2016). "Starting from genome-wide linkage analysis in two large families with autosomal dominant dilated cardiomyopathy (DCM), the identification of a mutation hotspot within RBM20 has directed the investigation on RBM20-regulated genes that may account for the development of cardiomyopathies." (PMID 32276354, 2020). "To exemplify this, we provide a brief overview of our evolving understanding of the molecular mechanisms in cardiac disease caused by pathogenic genetic variants in the AS factor RNA-binding motif protein 20 (RBM20), often referred to as RBM20 cardiomyopathy." (PMID 39773891, 2025). "High-risk features for each cardiomyopathy phenotype (HCM, DCM, ARVC) and gene-specific (Filamin C (FLNC), desmoplakin (DSP), RNA binding motif protein 20 (RBM20)) high-risk features are elaborated on in Chapter 7 of the ESC guideline." (PMID 40227490, 2025). "Among HTx recipients, a pathogenic mutation in the RBM20 gene was identified in one patient, while two others carried VUS in TTN and PKP2, which are genes associated with cardiomyopathies." (PMID 40126245, 2025). "An important question remaining after this discovery is to what extent each of these mechanisms—target gene missplicing and cytoplasmic RBM20 granules—contribute to the pathogenesis of RBM20 cardiomyopathy." (PMID 39773891, 2025). "As well, Guo and colleagues demonstrated that S107 blocked increased basal Ca2+ release and improved cardiac performance in a model of RNA-binding protein 20 (RBM20) cardiomyopathy." (PMID 36625865, 2023). "RBM20 cardiomyopathy accounts for approximately 3% of familial dilated cardiomyopathy (DCM) cases, with an increasing number of DCM-associated mutations having been identified." (PMID 37219949, 2023). "They offer mechanistic insights and functional annotation of RBM20 substrates that contribute to cardiomyopathy and heart failure." (PMID 35783855, 2022).
cardiomyopathy (continued). "Based on the RBM20 KO-mice model, considering verapamil as a specific treatment option of arrhythmogenic dilated RBM20-cardiomyopathy was the subject of another recent study." (PMID 34575212, 2021). "Recently, a novel angle on molecular pathophysiology of RBM20-related cardiomyopathy was established, exemplified by findings from gene-edited RBM20-p.Arg636Ser pigs." (PMID 34575212, 2021). "The majority of the VUS has been identified in genes previously having been reported to be associated with cardiac channelopathies (SCN5A, AKAP9, RYR2) and cardiomyopathies (RBM20, RAF1, DSG2)." (PMID 33789662, 2021). "Loss of Rbm20 results in reduced myocardial stiffness at younger age and overt RBM20 cardiomyopathy at older age in rats." (PMID 34523260, 2021). "As for many other genetic disorders, CRISPR/Cas9-based gene editing provides a powerful tool to investigate and possibly repair genetic abnormalities seen in RBM20-related cardiomyopathy." (PMID 34575212, 2021). "These insights into the mechanistic interactions provide a basis for the future development of RBM20 modulators which adapt titin elasticity in cardiomyopathies." (PMID 34575212, 2021). "Further research on RBM20, and treatment of RBM20 cardiomyopathy, will need to consider both the multitude and relative contribution of the different splicing targets and related pathways, as well as gender differences." (PMID 32789749, 2020). "Transgenic overexpression of CaMKIIδA alone is sufficient to induce a phenotype similar to RBM20 cardiomyopathy, and strikingly this largely affects male mice, leading to ~ 50% lethality at 8 weeks of age, while females are unaffected." (PMID 32789749, 2020). "In this review, we aim to summarize these recent insights in RBM20 cardiomyopathy, and provide possible new translational approaches based on these new insights." (PMID 32789749, 2020). "Together, these data suggest that the RBM20 cardiomyopathy phenotype is more severe and arrhythmogenic, and cannot be solely explained by changes in titin." (PMID 32789749, 2020). "For the remaining MYH7 HCM samples, variants in the following other cardiomyopathy genes were also found: DSP, MHY6, NEBL, PSEN1, RBM20, and TTN." (PMID 32344918, 2020). "Some genes are specific to one class of cardiomyopathy like RBM20 in DCM, whereas others like MYPN and TNNI3 are implicated in at least 3 different types of cardiomyopathy." (PMID 30764827, 2019). "The identified RBM20-dependant genes were enriched for genes related to ion-handling, sarcomere function and cardiomyopathy." (PMID 30050558, 2018). "RBM20, a member of the SRSF family, regulates the splicing of many genes that are linked to cardiomyopathy, including titin." (PMID 27914791, 2017). "In this narrative review, we focus on cardiomyopathy-associated genotypes consistently linked to high arrhythmic risk-LMNA, truncating variants in FLNC, RBM20, PLN p.Arg14del, and desmosomal genes-and examine their molecular mechanisms, phenotypic trajectories, and arrhythmogenic profiles." (PMID 42074488, 2026). "Hence, a putative mechanistic basis for RBM20 cardiomyopathy was established based on target gene missplicing." (PMID 39773891, 2025). "A severe variation of DCM is called RBM20 (RNA binding motif protein 20) cardiomyopathy." (PMID 41190030, 2025). "With further validation, this may indicate nuclear retention and or degradation of nuclear exported RBM20 mRNA as a potential mechanism of DOX-induced cardiomyopathy." (PMID 38566187, 2024). "Several RBPs, including RBM20 and RBFOX2, are associated with human cardiomyopathies." (PMID 38535111, 2024). "The following sections will discuss the recent understanding of well-characterized RBPs, including RBM20, RBM24, RBPMS, RBPMS2, RBFOX1, RBFOX2, and several readers of mRNA methylation, such as IGF2BP2 and YTHDC1, associated with cardiomyopathy in humans and/or animal models." (PMID 38535111, 2024).
cardiomyopathy (continued). "Disrupted splicing of RBM20 target genes is characteristic of RBM20 cardiomyopathy." (PMID 37219949, 2023). "Herein, employing a potentially novel RBM20 RS domain deletion mouse model in combination with in vitro experiments, we show that RBM20 mis-localization, rather than disrupted splicing, is the driving mechanism in RBM20 cardiomyopathy caused by NLS mutations." (PMID 37219949, 2023). "Further studies deciphering the role of RBM20 phosphorylation in alternative splicing in muscle tissues may aid the development of new strategies for the treatment of cardiomyopathies." (PMID 36140694, 2022). "Although there are several reports of truncating RBM20 mutations associated with cardiomyopathy, until now it is not completely understood how truncating variants contribute to the pathomechanism." (PMID 34201072, 2021). "In particular, missplicing of the RBM20-target calcium/calmodulin-dependent protein kinase II (CaMKII), a crucial modulator of E-C coupling in cardiomyocytes, is likely responsible for altered cellular calcium handling and cellular calcium overload observed in RBM20 cardiomyopathy." (PMID 34745372, 2021). "Importantly, our alternative splicing predictions further suggest a more complex model of the role of mutant RBM20 in cardiomyopathy pathogenesis." (PMID 34732726, 2021). "Consequently, the presence of these sarcoplasmic aggregations seems to play a relevant role in the pathophysiology of RBM20-related cardiomyopathy." (PMID 34575212, 2021). "It has also been reported that other splicing targets of RBM20 including important DCM-related genes, CACNA1C and CAMK2D, may be involved in the pathogenesis of cardiomyopathy caused by RBM20 mutations." (PMID 33928132, 2021). "RBM20-related cardiomyopathy is an excellent example of how structured, collaborative clinical and experimental research can further our knowledge to a degree where clinical decision-making is considerably improved, and molecularly guided therapeutic options are emerging." (PMID 34575212, 2021). "However, RBM20 related cardiomyopathies reveal a more severe clinical course when compared to titinopathies with e.g., earlier onset and severe disease expression." (PMID 33260757, 2020). "As a different regulation pattern of the TGFβ signaling pathway was observed in samples with mutations in RBM20 and PKP2, this pathway might play a distinct role in different forms of cardiomyopathies." (PMID 33260757, 2020). "Together, these results show that RBM20 cardiomyopathy is accompanied with an altered cellular calcium handling, which could be the reason for the heightened number of arrhythmias observed in patients." (PMID 32789749, 2020). "Interestingly, RyR2 transcripts containing this exon are upregulated in Rbm20-null rats as well as in cardiomyopathy patients." (PMID 30050558, 2018). "Whether these granules are detrimental as they are in RBM20 cardiomyopathy remains to be determined, but this finding provides at least some support that variants in other AS factors may also disrupt heart formation or promote failure through pathogenic cytoplasmic granules." (PMID 39773891, 2025). "Similarly to other cardiomyopathies, disease expression may vary depending on site-specific alterations in RBM20, so accounting that information in future projects will bring clinical value to such work." (PMID 33671899, 2021). "As RBM20 functions in the pre-mRNA splicing of the TTN gene, which provides connections at the level of individual microfilaments, loss of RBM20 inhibits muscle differentiation and leads to heart diseases such as cardiomyopathy and ischemic heart disease in vivo." (PMID 33789631, 2021). "While most research on RBM20 splicing targets has focused on titin (TTN), multiple studies over the last years have shown that other splicing targets of RBM20 including Ca2+/calmodulin-dependent kinase IIδ (CAMK2D) might be critically involved in the development of RBM20 cardiomyopathy." (PMID 32789749, 2020).
cardiomyopathy (continued). "Likewise, male patients with RBM20 cardiomyopathy also show a more severe disease phenotype [17•]." (PMID 32789749, 2020). "Dysregulation of alternative splicing - mediated by factors such as RBM20 or SLM2 - can affect proper gene isoform control, disrupting gene isoform homeostasis and underpins severe cardiomyopathy in both animal models and patients." (PMID 41530494, 2026). "Our group has previously elucidated the roles of two cardiac splicing factors in cardiomyopathy, including RBFOX1 as a heart failure-related splicing factor and RBM20 as a cause for non-compaction cardiomyopathy." (PMID 34273561, 2022). "Further study of alternative splicing of FHOD3 by RBM20 and PTB4 may contribute to exploring mechanisms and therapeutic targets of cardiomyopathy." (PMID 35783855, 2022). "The RBM20 mutations p.Gly603Arg (c.1807G > A) and p.Glu792GlyfsTer9 (c.2374dup) were inherited from the mother (III.3) who has arrhythmias but no cardiomyopathy." (PMID 34201072, 2021). "Notably, multiple studies have now shown that mice with disrupted splicing of RBM20 target transcripts do not develop an overt cardiomyopathy." (PMID 37219949, 2023). "Besides the cytoplasmic RBM20 granula, which might contribute to the cardiomyopathy phenotype, the absence of the mutant protein from nuclei resulting in a functional RBM20 haploinsufficiency leads to a missplicing in the patients." (PMID 34201072, 2021). "This splicing-centric view was challenged when mice expressing RBM20 lacking the RNA recognition motif (RRM) (Rbm20ΔRRM) were found to exhibit disrupted splicing of major RBM20 target genes and systolic dysfunction in the absence of cardiomyopathy." (PMID 37219949, 2023).
heart failure (33 papers, 2013 to 2025). Inability of the heart to pump blood at an adequate rate to meet tissue metabolic requirements. "Male carriers of RBM20 variants were more likely to progress to end-stage heart failure than female carriers." (PMID 39959410, 2025). "Eight RBM20 variant carriers died during follow-up (3 heart failure–related and 3 sudden cardiac deaths)." (PMID 37593875, 2023). "Altered Ca2+ cycling and cardiac contraction is well known in heart failure and was also demonstrated in iPSC-CMs with mutations causing defective sarcomere structures: S635A- in RBM20, E1680K in SPEG R173W in TNNT2." (PMID 37349842, 2023). "As shown here, RBM20 and SLM2 share several of their targets in the heart, including TTN, which are important parts of the heart failure phenotype observed in humans with mutated RBM20." (PMID 34273561, 2022). "RBM20 mutations lead to a severe form of DCM with high rates of heart failure, arrhythmias, and sudden cardiac death, a complex phenotype resulting from missplicing of several RBM20 target genes." (PMID 34745372, 2021). "We found a RBM20 variant (#1), which is a new gene annotated in 2009 and associated with early in life end stage heart failure, need for accelerated heart transplantation and early SCD." (PMID 29343803, 2018). "Pediatric patients with DCM carrying RBM20 mutations may present with early onset heart failure and arrhythmias, particularly, an increased risk of ventricular arrhythmias." (PMID 39959410, 2025). "In addition to titin, RBM20 can also regulate splicing of 30 more genes in the heart that are associated with the development of heart failure." (PMID 31614708, 2019). "Thus, high AF prevalence in the Rbm20S637A/S637A mice might be the consequence of heart failure, loss of RBM20-dependent alternative splicing, presence of cytoplasmic RBM20S637A protein, and other unknown defects." (PMID 33110103, 2020). "Modulating RBM20 activity to regulate titin isoform expression is currently being explored to alleviate elevated myocardial stiffness in heart failure with preserved ejection fraction (HFpEF)." (PMID 40119572, 2025). "RNA-binding protein RBM20 weakens splicing to orchestrate cardiac pre-mRNA processing, and contributes to the pathogenesis of heart failure." (PMID 36313471, 2022). "In summary, our mini review has illustrated a promising way to attenuate myocardial stiffness characterized in heart failure, which mainly depends on the role of splicing factor RBM20 on titin pre-mRNA to modulate titin isoforms ratio." (PMID 35783855, 2022). "In summary, our findings suggest that even though titin size switching occurs and myocardial stiffness is changed at younger age of Rbm20 KO rats, the overt phenotype of heart failure exhibits at older age." (PMID 34523260, 2021). "In this study, we further characterized the effect of RBM20 on the progression of heart failure with development in Rbm20 knockout (KO) rats." (PMID 34523260, 2021). "Supporting this idea is the enrichment of the identified RBM20 targets for tissue-specific diseases associated with RBM20 mutations (DCM, hypertrophic cardiomyopathy and heart failure) according to NCBI Medical Subject Heading (MeSH)." (PMID 30050558, 2018). "For instance, inhibition of RBM20 improves diastolic function in a mouse model of heart failure and reducing RBM20 can ameliorate cardiac atrophy." (PMID 29304022, 2018). "Remarkably, reduced expression of RBM20 has been identified in human heart failure influencing normal splicing of these target genes." (PMID 29304022, 2018). "Genotype-phenotype associations linked RBM20 mutations with aggressive DCM characterized by variable symptoms that include arrhythmias, heart failure and sudden death." (PMID 30050558, 2018). "Since RBM20 is a newly identified splicing factor in muscle tissue and an emerging target for heart failure treatment, we will discuss the role of RBM20 in heart disease in the remaining sections." (PMID 29304022, 2018).